GHRLOS (ghrelin opposite strand/antisense RNA)
Synonyms: NCRNA00068; GHRL-AS1; GHRLAS
Gene: Long non-coding RNA gene on chromosome 3 (10,285,754 to 10,294,903, forward strand). Ensembl gene ENSG00000240288.
Diseases named in the same sentence as GHRLOS in open-access papers:
GHRLOS is named in the same sentence as 15 diseases in open-access papers, as found by Europe PMC text mining. Sharing a sentence is not in itself a finding about the gene and the disease. The quoted sentences say what the papers report.
colorectal cancer (3 papers, 2021 to 2022). A primary or metastatic malignant neoplasm that affects the colon or rectum. "GHRLOS (LINC00852) was lowly expressed in colorectal cancer tissues, and decreased expression of GHRLOS was correlated with distant metastasis, lymph node metastasis and poor histological tumor grade." (PMID 34496800, 2021). "The level of lncRNA GHRLOS is reduced in human colorectal cancer tissues, and its high expression suggests a better prognosis." (PMID 33968785, 2021). "A recent study suggests that lncRNA GHRLOS is an inhibitor of cancer progression and may serve as a candidate biomarker of tumor metastasis and a prognostic indicator in colorectal cancer." (PMID 33968785, 2021).
gastric cancer (2 papers, 2021 to 2022). A primary or metastatic malignant neoplasm involving the stomach. "SMAD7, HIF-1α gene and HIF-1α protein may be jointly involved in tumor development and prognosis (act as oncogenic factors), while SEC13, GHRL, and lncRNA GHRLOS may act as tumor suppressor factors and thus could be considered as novel therapeutic targets for gastric cancer." (PMID 35449150, 2022). "As a new modulatory RNA molecule, GHRLOS (LINC00852) was up-regulated in gastric cancer tissues, and high expression of GHRLOS predicted poor overall survival in patients of gastric cancer." (PMID 34496800, 2021).
non-small cell lung carcinoma (2 papers, 2021 to 2025). A group of at least three distinct histological types of lung cancer, including non-small cell squamous cell carcinoma, adenocarcinoma, and large cell carcinoma. "Elevated levels of lncRNA GHRLOS significantly inhibited cancer cell proliferation and invasion while promoting apoptosis through the modulation of E-cadherin, N-cadherin, BAX, and Bcl-2 expression in non-small-cell lung cancer." (PMID 39940682, 2025).
breast carcinoma (1 paper, 2021). "In addition, high expression of GHRLOS promoted the proliferation and migration of breast cancer cells in vitro, and GHRLOS overexpression facilitated the orthotopic xenograft growth in vivo." (PMID 34496800, 2021).
chondrosarcoma (1 paper, 2008). A malignant cartilaginous matrix-producing mesenchymal neoplasm arising from the bone and soft tissue. "Levels of GHRLOS expression in the U-937 (Non-Hodgkin's lymphoma) and SW1353 (chondrosarcoma) cell lines were similar to the cerebellum, uterus, foetal brain, testis and thymus." (PMID 18954468, 2008). "The levels of GHRLOS expression were higher than GHRL in the thymus, whole brain, the SW1353 chondrosarcoma cell line, uterus and prostate." (PMID 18954468, 2008).
gastric MALT lymphoma (1 paper, 2021). "In gastric MALT lymphoma, lncRNA GHRLOS and another 44 mRNA were aberrantly expressed, in agreement with previous studies showing upregulation of lncRNA GHRLOS in different solid tumours." (PMID 35008340, 2021).
lentivirus infection (1 paper, 2021). Virus diseases caused by the Lentivirus genus. "To investigate the role of lncRNA GHRLOS in cancer cell proliferation, invasion, and apoptosis, we overexpressed lncRNA GHRLOS in A549 and NCI-H460 cells by lentivirus infection." (PMID 33968785, 2021).
liver cancer (1 paper, 2008). An epithelial or non-epithelial malignant neoplasm that arises from the liver. "Moreover, real-time RT-PCR showed extremely low levels of GHRLOS in the foetal and adult liver and high levels in the Hep G2 hepatocarcinoma cell line, suggesting that GHRLOS expression may be altered in liver cancer." (PMID 18954468, 2008).
ovarian carcinoma (1 paper, 2008). A malignant neoplasm originating from the surface ovarian epithelium. "However, total GHRL RNA levels were higher than GHRLOS in the pancreas and the OVCAR-3 ovarian cancer cell line." (PMID 18954468, 2008).
tumor (6 papers, 2019 to 2022). "Low levels of LncRNA GHRLOS in tumor samples of cancer patients were associated with a shorter survival." (PMID 31681567, 2019). "Downregulation of GHRLOS was associated with more aggressive tumor phenotype." (PMID 31681567, 2019). "LncRNA GHRLOS overexpression significantly inhibited tumor growth and decreased tumor weight in nude mice." (PMID 33968785, 2021). "Compared to adjacent normal tissue, 54.4% (199/366 cancer patients) of tumor specimens showed reduced GHRLOS transcript." (PMID 31681567, 2019). "SMAD7, HIF-1α gene, and HIF-1α protein may be jointly implicated in cancer development and prognosis, while SEC13, GHRL, and lncRNA GHRLOS may act as tumor suppressors." (PMID 35449150, 2022). "This may indicate that small-molecule drugs can affect HCC tumor progression and prognosis by acting on the GHRLOS." (PMID 35559014, 2022). "However, miR-346 overexpression markedly reversed lncRNA GHRLOS-induced suppression on tumor volume and weight." (PMID 33968785, 2021). "It was found that lncRNA GHRLOS was significantly downregulated in NSCLC tumors tissues and cancer cells compared with adjacent non-tumor tissues and the normal lung BEAS-2B cells." (PMID 33968785, 2021). "GHRLOS may act as a tumour suppressor during CRC development, and downregulation of its expression may facilitate tumour progression and metastasis." (PMID 35628187, 2022).
cancer (5 papers, 2008 to 2025). A tumor composed of atypical neoplastic, often pleomorphic cells that invade other tissues. "Colony formation and transwell assays demonstrated that miR-346 significantly increased cancer growth and cell invasion, but this effect was overturned by concomitant overexpression of lncRNA GHRLOS." (PMID 33968785, 2021). "lncRNA GHRLOS overexpression suppressed cancer cell invasion with downregulation of N-cadherin and upregulation of E-cadherin, that are epithelial-to-mesenchymal transition (EMT) associated biomarkers." (PMID 33968785, 2021). "Therefore, it can be suggested that lncRNA GHRLOS has comparable inhibitory effect on cancer cell as it is related to GHRL gene." (PMID 35449150, 2022). "Accumulating evidence shows that lncRNA GHRLOS and miRNA-346 play important roles in cancers." (PMID 33968785, 2021). "An examination of GHRLOS expression in cancer would, therefore, be of great interest." (PMID 18954468, 2008). "Furthermore, lncRNA GHRLOS repressed Bcl-2 and upregulated Bax expression in cancer cell lines." (PMID 33968785, 2021). "Taken together, these results suggest that by competitively absorbing miR-346, lncRNA GHRLOS upregulates APC and further regulates cancer cell proliferation, invasion, and apoptosis in NSCLC." (PMID 33968785, 2021).
GHRLOS also shares sentences with these, for which no sentence is quoted: lymph node metastasis (1 paper); non-Hodgkin lymphoma (1); prostate carcinoma (1); type 2 diabetes (1).